HPN (hepsin)
Diseases named in the same sentence as HPN in open-access papers (continued):
Sharing a sentence is not in itself a finding about the gene and the disease.
prostate carcinoma (continued). "Thus, LPB-Tag/PB-Hepsin model of prostate cancer was ideal for our analysis of Hepsin inhibitors, because the functional significance of Hepsin expression in these mice was already well established." (PMID 24657880, 2014). "Furthermore, Hepsin overexpression in the LNCaP human prostate cancer cell line grown as an orthotopic xenograft in mice promotes invasive tumor growth and lymph node metastasis." (PMID 24657880, 2014). "Hepsin is upregulated, which leads to the overexpression of the gene in prostate cancer tumors." (PMID 24213111, 2011). "Hepsin has been described to promote cancer progression and metastasis in a mouse model, but it seems to inhibit cell growth and invasion in prostate cancer cells." (PMID 17579619, 2007). "Thus, the oncogenic functions of hepsin could be mediated through activating MSP during prostate cancer progression and metastasis." (PMID 35204704, 2022). "Moreover, genomic amplifications of hepsin, not deletions or other alterations, were significantly associated with prostate cancer metastasis." (PMID 35204704, 2022). "The results from this study emphasize the importance of incorporating NETO2, HPN, AR, and KLK3 as part of a comprehensive model for prostate cancer prognosis, pointing towards their potential to improve clinical outcomes." (PMID 40034593, 2025). "An in vitro study provided further evidence that hepsin interacts with the miR-222/AKT axis, promoting epithelial–mesenchymal transition (EMT) and cell invasion in prostate cancer." (PMID 35204704, 2022). "Therefore, hepsin could be a novel biomarker and a therapeutic target for prostate cancer." (PMID 35204704, 2022). "Therefore, hepsin could be a novel biomarker and therapeutic target for prostate cancer." (PMID 35204704, 2022). "Expression of HPN is strongest in PIN and still highly expressed in primary prostate cancer with expression receding in metastatic disease." (PMID 35948756, 2022). "The reference-free diagnostic panel used the ratio of relative expression of three mRNAs that are overexpressed (FOLH1, XBP1 and HPN) to five mRNAs that are underexpressed (ITSN1, GSTM4, LTBP4, NELL2, and CFD) in prostate cancer compared to normal tissue." (PMID 33172003, 2020). "Similar to the crucial role of HAI-1’s KD1 on HGFA and hepsin, we found that HAI-2’s KD1 exhibits a potent inhibition on matriptase activity and prostate cancer cell invasion." (PMID 29118397, 2017). "LPB-Tag/PB-Hepsin mice upregulate expression of SV40 large T antigen and Hepsin in the prostate epithelium and develop primary prostate cancer with metastatic lesions in approximately 55% of the animals." (PMID 24657880, 2014). "RNA from a dilution series of prostate cancer lines C4-2 and PC3 was prepared, and hybridized to a probe library of six selected genes: KLK3, CD90/THY1, AGR2, HPN, PCA3, UPK3A." (PMID 23029164, 2012). "Other seminal plasma proteases with matrix-regulation activities include TMPRSS2 (the most common fusion partner of ERG), HPN and PSA, all previously shown to be up-regulated in prostate cancer." (PMID 21814574, 2011). "In the Prostate Cancer dataset, we identified some important genes with significant biological relevance, such as TMSB15A, PEDF, hepsin, KIAA0977, and S100A4." (PMID 19874631, 2009). "Our data identify the transmembrane serine proteases hepsin and matriptase-1 (MTSP1) as potentially strong prognostic markers of prostate cancer." (PMID 15928670, 2005). "A number of genes including hepsin, myc, fatty acid synthase SPARC1 and EBNA-2 coactivator show similar expression patterns across multiple prostate cancer studies, and are also regulated in our study." (PMID 15892885, 2005). "Hepsin, a cell surface serine protease, is a potential biomarker for the detection of prostate cancer due to its high expression in prostate cancer but not in normal prostate." (PMID 36145330, 2022).
prostate carcinoma (continued). "It seems paradoxical that HPN plays a role in HCC based on its down-regulation in our and other reports, as its level was up-regulated in other cancers such as ovarian carcinoma, renal cell carcinoma, and prostate cancer as reported in previous studies." (PMID 35164791, 2022). "Tissue microarray-based expression profiling demonstrated that hepsin expression was upregulated in prostate cancer specimens, but low or no hepsin expression was detected in normal prostate and BPH specimens." (PMID 36145330, 2022). "Hepsin is not overexpressed in prostate cancer cell lines and overexpression of Hepsin in cells in culture results in cell detachment and downregulation of cell proliferation." (PMID 24657880, 2014). "Although the gene signatures of all forms of urogenital cancer/diseases are largely unknown, the six known prostate cancer genes of AGR2, AMACR, CRISP3, ERG, HPN, and PCA3 are at or below background, for example, in bladder cancer." (PMID 23029164, 2012). "Differential expression analysis revealed genes that have been previously reported to be up regulated in prostate cancer, e.g. HPN and AMACR (data not shown)." (PMID 21912659, 2011). "Although the lack of detection of hepsin in either urine or serum makes its use as a biomarker difficult, this gene and its protein product has the potential to be utilized in prostate cancer detection." (PMID 24213111, 2011). "Genes over-expressed in prostate cancer include AMACR, HPN, RDH11, and TMPRSS2." (PMID 16638148, 2006). "In addition, we identified another marker gene, Hepsin (HPN), with a 0.930 area under the curve score distinguishing normal tissue from prostate cancer lesion." (PMID 33032611, 2020). "While HPN is not amplified in prostate cancer, it is one of the most prominently overexpressed genes in the majority of human prostate tumors and genetic experiments in mice indicate that Hepsin promotes prostate cancer metastasis, particularly metastasis to the bone marrow." (PMID 24657880, 2014). "Using a histogram format for data display, all signal counts for the selected prostate cancer genes were at background for P08-022N: AGR2 = 0.08 [(8 counts, relative to B2M = 100 (10,000 counts)], AMACR = 0.46, CD90v = 0.02, CRISP3 = 0.25, ERG = 0.1, HPN = 0.04, PCA3 = 0.09 (data entries in blue)." (PMID 23029164, 2012).
breast carcinoma (15 papers, 2013 to 2024). "To investigate the disease-specific variants of hPn, we examined the expression of hPn-ASVs in breast cancer tissues." (PMID 39334860, 2024). "Here, we show that genetic deletion of the gene encoding hepsin (Hpn) in a WAP-Myc model of aggressive MYC-driven breast cancer inhibits tumor growth in the primary syngrafted sites and the growth of disseminated tumors in the lungs." (PMID 37872868, 2023). "In gastric cancer, elevated HPN levels are associated with a worse prognosis, whereas in breast cancer, low HPN levels predict worse survival." (PMID 35804878, 2022). "Curiously, low expression of HPN was associated with poor survival in breast cancer, renal cell carcinoma, and hepatocellular carcinoma." (PMID 32630086, 2020). "In contrast to our results, a previous study presented that hepsin overexpression was associated with positive nodal status and tumor stage in breast cancer." (PMID 26014348, 2015). "Analysis of transcript co-regulation in our samples showed that additional genes are expressed in parallel with GATA3, including those coding for carbonic anhydrase XII (CA12), cyclin D1 (CCND1) or hepsin (HPN), all of which have been associated with breast cancer." (PMID 24205108, 2013). "This is in agreement with other studies on HPN in prostate and breast cancer, and the underlying functional mechanism could be based on the ability of HPN to promote invasion to distant organs through the disorganization of the basement membrane that surrounds the primary tumor." (PMID 35804878, 2022). "The ratio of Pn expression in breast cancer tissue to NAT was higher in hPn-ASVs with exon 21 than all hPn-ASVs by 1.6–5.2-fold in four patients and lower in two patients (by 0.5- and 0.8-fold, respectively)." (PMID 39334860, 2024). "Hepsin, a type II transmembrane serine protease, is commonly overexpressed in prostate and breast cancer." (PMID 37872868, 2023). "Analyzing the ovarian cancer and breast cancer TCGA datasets also confirmed the increases in hepsin mRNA levels in the ovarian and breast cancer tissues in comparison with their normal counterparts." (PMID 35204704, 2022). "The increased expression of hepsin at both the mRNA and protein levels has been reported in some solid cancers, including prostate, ovary, kidney, and breast cancers." (PMID 35204704, 2022). "In a recent breast cancer study, the expression of hepsin was reduced in tumors when compared with adjacent healthy tissue." (PMID 31399560, 2019). "In vitro, ubiquitination and proteasomal degradation of hepsin occurred in response to cathepsin D expression in breast cancer cells, which led to increased metastasis in an in vivo model." (PMID 31399560, 2019). "It was shown recently that hepsin becomes mislocalized when liver kinase B1 (lkb1) expression is lost and that overexpressed hepsin induces basement membrane degradation in breast cancer." (PMID 26014348, 2015). "In closing, this study expands our knowledge of the biological processes behind breast cancer by investigating hepsin and TMPRSS3 expression in human breast tumors." (PMID 26014348, 2015). "Immunohistochemical staining was used to evaluate hepsin levels in 372 breast cancer samples and TMPRSS3 levels in 373 samples." (PMID 26014348, 2015). "SPINT1, which is one of the Kunitz-type serine protease inhibitors and also known as HAI-1, can inhibit hepatocyte growth factor function via regulation of HGFA, matriptase, and hepsin to inhibit the migration, proliferation, and invasion of breast cancer, indicating a good prognosis." (PMID 33336077, 2021). "Low expression levels of hepsin and TMPRSS3 are associated with poor breast cancer survival." (PMID 27841306, 2016). "Structurally, TMPRSS3 is almost identical to hepsin, and here we have shown that their mRNA and protein expression patterns are very similar in different phases of breast carcinogenesis and correlate with breast cancer prognosis." (PMID 26014348, 2015).
breast carcinoma (continued). "When overexpressed in breast cancer, hepsin and TMPRSS3 could promote cancer cell invasiveness via dysregulated proteolytic activity." (PMID 26014348, 2015). "Similarly, low protein expression of hepsin (log rank, P = 0.035) predicted poorer breast cancer-specific survival during the 10-year follow-up period, yet was not significant during the 20-year follow-up period (P = 0.315)." (PMID 26014348, 2015). "Consequently, combined TMPRSS1 and TMPRSS3 mRNA expression and combined hepsin and TMPRSS3 protein expression were tested for statistical association with clinicopathological parameters and breast cancer-specific survival." (PMID 26014348, 2015). "We further demonstrate in 3D cultures of patient-derived breast cancer explants that both basal TGFβ signaling and EGFR protein expression are inhibited by neutralizing antibodies or small-molecule inhibitors of hepsin." (PMID 37872868, 2023). "We think that our results give emphasis to the role of altered expression of hepsin and TMPRSS3 in promoting breast tumor progression and metastasis as their role in breast cancer is still rather unexplored." (PMID 26014348, 2015). "However, the first hepsin expression study in MDA-MB-231 and HER18 breast cancer cell lines showed that low hepsin expression levels reduced cell viability and the colony formation rate." (PMID 26014348, 2015). "The results suggest that the TTSPs hepsin and TMPRSS3 may have similar biological functions in the molecular pathology of breast cancer." (PMID 26014348, 2015). "These previous findings prompted us to investigate whether altered expression of hepsin and TMPRSS3 might also have a role in the molecular pathology of breast cancer." (PMID 26014348, 2015).
prostate tumor (9 papers, 2007 to 2022). "The majority of studies devoted to evaluating the role of hepsin in oncopathology have focused on tumors of the prostate." (PMID 22649671, 2011). "In this study, we developed a novel PET radioligand for hepsin imaging in prostate tumor." (PMID 36145330, 2022). "Considering the characteristics of the LPB-Tag/PB-Hepsin model, we anticipated that we would need to treat animals with HepIn-13 for a relatively long duration, starting at 10 weeks of age, when the animals present with low-grade prostate tumors." (PMID 24657880, 2014). "We propose the following hypothesis: an increase in hepsin proteolytic activity on a cell surface is specific of prostate tumors." (PMID 22649671, 2011).
hepatocellular carcinoma (7 papers, 2004 to 2022). A malignant tumor that arises from hepatocytes. "The expression ratio between #6185 (Human hepatoma mRNA for serine protease hepsin) and #5840 (Homo sapiens mRNA for KIAA1109 protein) was able to discriminate 92.2% of total tissues." (PMID 15469618, 2004). "The human hepatoma mRNA for serine protease hepsin had been determined to be an important marker for cancer cell development." (PMID 15469618, 2004). "From the prostate dataset, the most cancer-correlated gene is the human hepatoma gene coding for serine protease hepsin." (PMID 15469618, 2004). "On the other hand, the expression ratio between #6185 (Human hepatoma mRNA for serine protease hepsin) and #6749 (Homo sapiens mRNA for KIAA1055 protein) was able to discriminate 90.10% of total tissues." (PMID 15469618, 2004). "The human hepatoma mRNA for serine protease hepsin was discussed in the previous section." (PMID 15469618, 2004).
colorectal cancer (6 papers, 2020 to 2023). A primary or metastatic malignant neoplasm that affects the colon or rectum. "Hepsin overexpression increased colorectal cancer cell invasion, Erk1/2 and STAT3 phosphorylation, and thrombin generation in plasma." (PMID 37275957, 2023). "A virtual screening of a database containing more than 2000 FDA-approved compounds was performed to screen hepsin inhibitors, and selected compounds were tested in vitro for their ability to suppress hepsin effects in colorectal cancer cells." (PMID 37275957, 2023). "Hepsin is a potential thrombotic and metastatic biomarker in patients with localized colorectal cancer." (PMID 35804878, 2022). "In addition, we identified venetoclax as a potent hepsin inhibitor that reduced the metastatic and prothrombotic phenotypes of hepsin-expressing colorectal cancer cells." (PMID 37275957, 2023). "The effect of hepsin levels on cell migration, invasion, and proliferation, as well as on the activation of crucial cancer signaling pathways, was performed in vitro using colorectal cancer cells." (PMID 37275957, 2023). "Likewise, they demonstrate the antitumor role of venetoclax as a hepsin inhibitor, laying the groundwork for molecular-targeted therapy for colorectal cancer." (PMID 37275957, 2023). "This could be relevant in tumors with a high prevalence of Ras mutations, such as colorectal cancer (CRC), where the implication of hepsin is practically unknown." (PMID 37275957, 2023). "This study aims to explore the molecular role of hepsin in colorectal cancer." (PMID 37275957, 2023). "In colorectal cancer, the role of hepsin is unknown, so we aimed to study the correlations between its expression and clinical-histopathological variables of patients with this cancer." (PMID 35804878, 2022). "A limited number of reports in the literature would suggest that HPN might play a more or less crucial role in colorectal cancer (CRC), although the relevance of the enzyme in this context has not been thoroughly evaluated." (PMID 35804878, 2022). "In addition, this article brings to light new information about the implication of hepsin in colorectal cancer." (PMID 35804878, 2022). "The hepsin/TMPRSS subfamily is a subclassification of the TTSP family and includes transmembrane protease serine 13 (TMPRSS13), a protein whose ability to promote breast and colorectal cancer (CRC) progression in vivo due to its antiapoptotic properties has been recently reported." (PMID 36085166, 2022).
ovarian carcinoma (6 papers, 2004 to 2022). A malignant neoplasm originating from the surface ovarian epithelium. "Indeed, hepsin activity is important for prostate and ovarian cancer cell invasion, a process linked to metalloproteinase activity in many circumstances." (PMID 29196708, 2017). "Hepsin upregulation in malignant tumors has been demonstrated in prostate and ovarian cancers as well as in renal cell carcinoma." (PMID 26014348, 2015). "HPN, for example, was marginally overexpressed in both primary and secondary ovarian cancer tissue, compared to the normal ovary (approx. two-fold)." (PMID 14760385, 2004).
renal cell carcinoma (5 papers, 2015 to 2025). "They suggested that hepsin may be involved in both the early and late development of renal cell carcinoma." (PMID 26014348, 2015). "In another urological cancer, increased expression of hepsin and decreased expression of HAI-2 have been reported to correlate with poor prognosis in patients with renal cell carcinoma (RCC)." (PMID 40299447, 2025).